INS (insulin)
Diseases named in the same sentence as INS in open-access papers (continued):
Sharing a sentence is not in itself a finding about the gene and the disease.
Insulin resistance (continued). "Higher Cu levels in metabolic syndrome (MS) patients are also associated with insulin resistance, further supporting a positive correlation between serum Cu and insulin levels within certain ranges, possibly linked to obesity and lipid metabolism abnormalities." (PMID 41268170, 2025). "Insulin resistance may accelerate bone loss by affecting insulin signaling pathways in bone metabolism, whereas inflammation and oxidative stress directly affect bone resorption and formation, leading to reduced bone density." (PMID 40235664, 2025). "High levels of estradiol have been shown to inhibit insulin signaling and induce cellular insulin resistance, which could explain the inverse association between early menarche and higher fasting glucose and fasting insulin in the study." (PMID 38912813, 2025). "Genetic factors connected with insulin resistance can be classified into genetic defects leading to abnormal insulin structure, genetic mutations in the insulin signaling system, genetic defects related to substance metabolism, and other relevant genetic anomalies." (PMID 40141412, 2025). "Moreover, since the development of insulin immunoassays, it has become clear that type 2 diabetes is often associated with both insulin resistance and decreased insulin production." (PMID 40284198, 2025). "Its serum levels are lower in women with PCOS compared to insulin-sensitive women, and it may be a cytokine linked to insulin resistance in women with PCOS." (PMID 40066975, 2025). "Dietary Se‐deficiency increased fasting insulin (54%) and glucose (33%) concentrations in postmortem sera, induced glucose intolerance (38%) and insulin resistance (31%), and decreased (27%–56%) baseline levels of skeletal muscle p‐AKT S473 and T308, as well as liver p‐AKT S473." (PMID 40540389, 2025). "Furthermore, weight loss enhances peripheral insulin sensitivity, thereby disrupting the vicious cycle in which hepatic insulin resistance contributes to ongoing fat synthesis and inflammation." (PMID 41153720, 2025). "High insulin levels and insulin resistance are suggested to be associated with reduction of IDE." (PMID 41169480, 2025). "Among these disorders are abdominal obesity, dyslipidemia, arterial hypertension, and abnormalities in glucose metabolism associated with insulin resistance, which is a pathophysiological phenomenon in which the biological action of insulin in the tissues is altered." (PMID 40647157, 2025). "Therefore, impaired insulin signaling in skeletal muscle is a hallmark of obesity-induced insulin resistance and metabolic dysfunctions." (PMID 40451926, 2025). "The American Diabetes Association (ADA) defines insulin resistance as a condition characterized by decreased tissue responsiveness to insulin; on the other hand, gestational diabetes mellitus (GDM) is defined as a carbohydrate intolerance that develops during pregnancy." (PMID 40361947, 2025). "Insulin treatment may play an important pathogenic role in predisposing individuals with T1D to insulin resistance." (PMID 39998445, 2025). "Individuals with overweight (BMI ≥ 24 kg/m2) are often accompanied by decreased insulin sensitivity, an increased risk of insulin resistance, and weakened ability to regulate postprandial glucose on their own (such as delayed insulin secretion and reduced glucose uptake by peripheral tissues)." (PMID 41228506, 2025). "Furthermore, phenylalanine is not only linked to insulin resistance but also with reduced insulin secretion." (PMID 40289598, 2025). "It has shown that Val109Asp polymorphism genetic variation may alter insulin metabolism and insulin resistance and play a key role in the development of T2DM." (PMID 40770752, 2025). "These medications exert their effects through an array of diverse mechanisms, including enhancing insulin secretion from pancreatic beta-cells, promoting weight loss, reducing peripheral insulin resistance, decreasing mitochondrial oxidative stress, and minimizing fat absorption." (PMID 40149950, 2025).
Insulin resistance (continued). "Indeed, white adipose tissue has long been implicated in the development of insulin resistance through production of adipocytokines and other lipid derivatives that impair insulin signaling." (PMID 40273152, 2025). "Moreover, obesity and elevated serum insulin levels have been shown to be associated with insulin resistance." (PMID 41002956, 2025). "Furthermore, obesity is frequently linked to insulin resistance, and insulin has been observed to stimulate the conversion of T4 to T3." (PMID 40678775, 2025). "In mice, sphingomyelins and ceramides have been associated with impaired glucose tolerance and insulin resistance, and accumulation of ceramides in skeletal muscle and adipocytes in vitro has been shown to impair insulin signaling, resulting in reduced insulin sensitivity." (PMID 39841244, 2025). "Expression of genes in both pathways (for which there is some overlap) has been previously associated with insulin sensitivity, suggesting that heritable variation in regulation of these pathways may influence risk of insulin resistance." (PMID 40595617, 2025). "Moreover, in mice, BACH1 is shown to be involved in regulating oxidative stress, a factor in obesity-associated insulin resistance, while its hepatic deletion improves insulin signalling and glucose metabolism by modulating key protein interactions." (PMID 40118008, 2025). "NKT cell subsets exhibit diverse effects on obesity-induced inflammation; they can promote insulin resistance by secreting inflammatory cytokines, particularly in response to excess lipids associated with obesity, but can also enhance insulin sensitivity through the secretion of Th2-type cytokines." (PMID 40559402, 2025). "In fact, insulin resistance in T1D has been linked to coronary atherosclerosis, cardiovascular disease, diabetic nephropathy and all-cause mortality, and it is partly driven by subcutaneously administered exogenous insulin itself." (PMID 40004833, 2025). "Conversely, a lower G/I ratio, associated with elevated insulin, may indicate insulin resistance and/or obesity, both of which are known to impair androgen synthesis across species." (PMID 40646763, 2025). "Thus, in CD36 deficiency, microvascular insulin resistance paradoxically associated with enhanced insulin sensitivity of glucose disposal." (PMID 39503770, 2025). "Early pregnancy causes a hormonal surge which leads to insulin resistance; some studies have shown the insulin-resistant states of gestational hyperglycemia to be associated with worse neonatal outcomes and greater need for neonatal ICU admissions when compared to insulin-deficient states." (PMID 39925506, 2025). "While selective insulin resistance seen in diabetic patients is a major driver of fatty liver disease, complete loss of hepatic insulin signaling is known to ameliorate MASLD, so we asked whether Tbx3 might induce complete insulin resistance." (PMID 40638249, 2025). "Similarly, the reduction in NMNAT1 expression, by unbalancing NAD+ homeostasis, causes mitochondrial dysfunction, is associated with insulin resistance, and impairs hepatic insulin signaling and hepatokine expression." (PMID 40724814, 2025). "Additionally, research comparing the impact of caloric restriction and the 5:2 diet over 4.5 months demonstrated greater declines in insulin levels and insulin resistance in the IF group despite significant weight loss in both groups." (PMID 40777199, 2025). "Consequently, disturbances in insulin homeostasis can be strongly associated with obesity and dyslipidemia; moreover, insulin resistance (IR) results in elevated androgen secretion and decreases the synthesis of sexual hormone binding protein (SHBG)." (PMID 41463090, 2025). "Previous research on T2D has suggested that impaired fetal nutrition during late gestation may induce permanent changes in β-cell function or insulin sensitivity, predisposing to adult insulin resistance." (PMID 41227152, 2025).
Insulin resistance (continued). "In addition, the low-grade inflammation associated with obesity causes metabolic changes such as insulin resistance, which leads to increased circulating insulin and IGF-1 levels." (PMID 40496310, 2025). "In addition, higher fasting insulin levels during childhood have been associated with the development of insulin resistance, abnormal glucose tolerance, and obesity in the following 6 years." (PMID 41009753, 2025). "The increased CRC risk observed with insulin and TZDs may be partly attributed to insulin resistance and hyperinsulinemia, which are common in patients requiring these therapies." (PMID 39980820, 2025). "Moreover, scavenging ROS generation significantly improves hepatic insulin sensitivity, providing compelling evidence for the causal relationship between hepatic oxidative stress and insulin resistance." (PMID 39859525, 2025). "Although insulin resistance might lead to an increase in glucose-induced insulin secretion in some PCOS patients, there are also other causes of hyperinsulinemia." (PMID 40013621, 2025). "As MAFLD is linked with insulin resistance, their ability to enhance insulin sensitivity also means that SGLT2 inhibitors may decrease hepatic glucose production and reduce circulating free fatty acid levels." (PMID 39860434, 2025). "The greater concentration of dietary insulinogenic amino acids (IAA) is known to increase insulin secretion and hyperinsulinemia, which could eventually increase the risk of insulin resistance and T2D." (PMID 40431415, 2025). "Moreover, T2D individuals with high insulin resistance who are treated with insulin have a higher risk of diabetic kidney disease and cardiovascular events." (PMID 40562310, 2025). "Our findings indicate that people with higher consumption of potato fries/chips might experience higher insulin response and insulin resistance, potentially leading to a higher risk of T2D in the future." (PMID 38747471, 2025). "Moreover, regular physical activity has been shown to reduce the risk of obesity-related health conditions, such as insulin resistance and cardiovascular diseases, by enhancing insulin sensitivity and promoting cardiovascular fitness." (PMID 40556926, 2025). "Insulin resistance has been linked to muscle wasting and low muscle mass, so improved insulin sensitivity could help mitigate these effects and contribute to better muscle health." (PMID 39893829, 2025). "The primary cause of glucotoxicity is insulin resistance, which arises from defective islet cell function and damage caused by reduced insulin mRNA expression, associated with diminished transcription or activity of transcription factors involved in insulin production (Daniël and Michaëla, 2011)." (PMID 39995417, 2025). "Oestrogen deficiency may exacerbate insulin resistance, dyslipidaemia, and vascular dysfunction, while glycaemic variability and altered insulin requirements are frequently reported during the menopause transition." (PMID 41334715, 2025). "Physiological evidence suggests that this polymorphism affects blood lipid levels and insulin sensitivity, as the Ser allele carriers exhibit higher levels of insulin resistance and lipid dysregulation, which can lead to worse outcomes in patients already suffering from metabolic comorbidities." (PMID 40150043, 2025). "Notably, normal pregnancy requires elevated glucose production and decreased insulin sensitivity to provide the energy required for the fetus; thus, there is an association between pregnancy and the progression of maternal insulin resistance." (PMID 41488874, 2025). "However, in a context of endothelial insulin resistance, there is a selective decrease in insulin-mediated effects on the PI3K-AKT-eNOS pathway, causing an imbalance between NO and endothelin-1 production." (PMID 41373661, 2025).
Insulin resistance (continued). "When this intricate Gut-X crosstalk is disrupted by factors like dysbiosis, poor diet, and genetic predisposition, the result is a convergence of insulin resistance, impaired insulin secretion, inflammation, and weight gain that manifest as T2D and its complications." (PMID 40871736, 2025). "A blunted insulin‐induced suppression of FA mobilization can lead to a persistent elevation in systemic FA availability, which is a major factor underlying the development of insulin resistance in obesity." (PMID 39487600, 2025). "It has been reported that the deficiency of ASGR1 may alleviate diet‐induced systemic insulin resistance via improved hepatic insulin sensitivity." (PMID 39949133, 2025). "In the present study, the plasma levels of long-chain ceramide C18:1 were inversely associated with insulin sensitivity (i.e., higher levels indicated greater insulin resistance), whereas levels of very-long-chain ceramide C26:0 were positively associated with insulin sensitivity." (PMID 40630937, 2025). "This will affect the production of insulin, and the risk of insulin resistance will increase." (PMID 39817379, 2025). "Furthermore, it enhances glucose-dependent insulinotropic polypeptide (GIP) secretion and improves insulin sensitivity, counteracting hyperuricemia caused by insulin resistance." (PMID 41031353, 2025). "Additionally, insulin resistance and high levels of insulin (hyperinsulinemia) have been associated with an increased risk of certain types of cancer, including breast, colon, and pancreatic cancers." (PMID 40491970, 2025). "In addition to leptin, adipokines such as resistin, which is linked to inflammation and insulin resistance, also likely to decrease with improvements in adiposity and insulin sensitivity." (PMID 41309556, 2025). "In PD, both insulin deficiency and insulin resistance contribute to impaired brain insulin signaling which may drive neuroinflammation, mitochondrial dysfunction, and oxidative stress." (PMID 40595707, 2025). "In contrast, those with a high pPGS associated with insulin resistance mechanisms may require targeted therapies to improve insulin sensitivity." (PMID 41001674, 2025). "Persistent decreases in energy intake may promote body weight loss, which subsequently enhances insulin sensitivity, diminishes hepatic steatosis, and alleviates systemic inflammation—key pathophysiological mechanisms driving insulin resistance in T2D." (PMID 41228539, 2025). "-Inversely associated with obesity in premenopausal women.-Associated with insulin sensitivity in premenopausal women.-Hyperestrogenemia is associated with insulin resistance.-In twin men discordant for obesity (n=18 pairs), E2 levels are higher in the heavier twin." (PMID 41180177, 2025). "Although severe insulin resistance may occasionally also play a role, the condition is most frequently linked to variations in genes that control beta-cell function and insulin secretion." (PMID 41323015, 2025). "Significant consequences of systematic consumption of high doses of zinc also include oxidative stress and low-grade chronic inflammation, with the latter consistently associated with insulin resistance due to impaired insulin signaling during activation of the NF-κB and JNK inflammatory pathways." (PMID 41439937, 2025). "Importantly, elevated fasting glucose and elevated insulin driven by insulin resistance has been associated with pancreatic cancer." (PMID 40094000, 2025). "Thus, myostatin can be associated with insulin resistance (IR), the connection being confirmed by previous research that revealed increased myostatin levels in obesity and enhanced insulin sensitivity and glucose uptake after myostatin expression loss." (PMID 41515940, 2025).
Insulin resistance (continued). "Resistin is another adipokine implicated in the pathophysiology of insulin resistance and is found at elevated levels in individuals with a higher BMI, showing strong positive correlations with leptin and insulin concentrations, thereby reinforcing its involvement in glucose dysregulation." (PMID 41334336, 2025). "Exercise-induced increases in myonectin levels may contribute to improved insulin sensitivity and glucose uptake in skeletal muscle, reducing insulin resistance and the risk of developing T2DM." (PMID 40134450, 2025). "For these low-risk women, weight loss may potentially lead to a higher loss of fat mass, decreasing regional adipose tissue depots, enhancing insulin sensitivity, alleviating insulin resistance, and potentially lowering the risk of late gestational diabetes." (PMID 41334337, 2025). "The risk is increased by elevating insulin resistance and/or decreasing insulin sensitivity." (PMID 40822418, 2025). "Although WC is now widely accepted as a surrogate for central adiposity and metabolic risk, the extent to which WC truly reflects underlying insulin resistance, as measured by serum insulin or HOMA-IR, remains unknown." (PMID 41302993, 2025). "Furthermore, low vitamin D status is linked to insulin resistance and increased BMI, potentially due to its role in reducing insulin secretion and receptor activity." (PMID 40149685, 2025). "Previous studies have shown that sulfonylureas are associated with weight gain due to increased insulin production, which could further contribute to insulin resistance." (PMID 40017057, 2025). "Notably, persistent high leptin levels in obesity can itself cause neuronal insulin resistance by impairing hypothalamic insulin signaling, worsening glucose imbalance." (PMID 40869170, 2025). "Until the beginning of the 21st century, insulin resistance itself was regarded as the origin of disorders leading to metabolic syndrome and type-2 diabetes, while the associated excessive insulin synthesis seemed to be a compensatory action helping cellular glucose uptake." (PMID 41514592, 2025). "Altered glucagon and insulin signaling contribute to T2D, and insulin resistance may also be associated with cognitive decline." (PMID 40271226, 2025). "The loss of FOXO1 and PDX1 transcription factor signaling in pancreatic β-cells, which results in the loss of insulin production prevalent in pathological conditions such as insulin resistance and T2DM, has been broadly demonstrated and identified as a key clinical target 1,40,41." (PMID 40585255, 2025). "T2D is characterized by insulin resistance, impaired insulin secretion, and relative insulin deficiency, with a pathophysiology influenced by genetic, environmental, and lifestyle factors, leading to hyperglycemia and severe complications if not managed effectively." (PMID 39926598, 2024). "Among these hormones, insulin, cortisol, and sex hormones are associated with insulin resistance." (PMID 38957446, 2024). "One hypothesis suggests that compensatory insulin resistance, a hallmark of type 2 diabetes, leads to elevated serum insulin levels, which may be linked to thyroid nodule formation." (PMID 39444449, 2024). "In this study, we tested the hypothesis that a decrease in metabolic rate that occurs in TN-adapted mice causes insulin resistance and that this reduction in insulin action and EE is reversed upon short–term transition to RT." (PMID 38354854, 2024). "Pathological states occurring with insulin resistance are associated with oxidative stress, which may affect interactions between vasopressin and insulin." (PMID 39769071, 2024). "Furthermore, progeny exposed to IUGR exhibit heightened insulin resistance, with impaired insulin sensitivity linked to low birth weight." (PMID 39201737, 2024). "Moreover, this type of obesity contributes to the reduction in tissue insulin sensitivity, the development of insulin resistance, and the risk of developing type 2 diabetes." (PMID 39683641, 2024).